MTOR (mechanistic target of rapamycin kinase)
Diseases named in the same sentence as MTOR in open-access papers (continued):
Sharing a sentence is not in itself a finding about the gene and the disease.
cervical carcinoma (continued). "Therefore, our study demonstrated that mTOR might act as an important factor governing the cross talk between apoptosis and autophagy in human cervical cancer cells." (PMID 26311737, 2015). "Our study suggested that AZD8055-mediated cervical cancer cell proliferation inhibition may occur through deregulating mTOR activity and upregulating the expression of miR-143, whose targets include HK2, a key time-limiting enzyme in the process of glucose activation." (PMID 23420667, 2013). "GCH1 knockdown impaired growth, migration and invasion and promoted apoptosis in cervical cancer cells, possibly through the inhibition of the phosphorylated PI3K/AKT/mTOR signaling pathway." (PMID 41583517, 2026). "Our findings suggest that RACK1 plays a regulatory role in lipid metabolism by activating the AKT/mTOR/SREBP1 signaling pathway, thereby promoting fatty acid synthesis in cervical cancer cells." (PMID 39425259, 2025). "Isoflurane inhibits the viability of cervical cancer cells, induces apoptosis, enhances oxidative stress, and induces autophagy by activating AMPK/mTOR pathway." (PMID 40309242, 2025). "Observations of proliferation arrest, inactivation of the Akt-mTOR pathway, and the induction of apoptosis were noted in GJB5-depleted cervical cancer xenograft tissues." (PMID 40537499, 2025). "In cervical cancer, abnormal activation of the PI3K/AKT/mTOR pathway plays a key role in carcinogenesis, particularly in HPV-positive lesions." (PMID 40647429, 2025). "In summary, the results show that PPP1R13L promotes cervical cancer cell proliferation, EMT, cycle progression, and glycolysis through the PTEN/AKT/mTOR pathway." (PMID 40014097, 2025). "Dysregulation of the PI3K/Akt/mTOR axis—frequently due to genetic alterations in components such as PIK3CA, PTEN, Akt and mTOR—is a common event in cervical cancer and contributes to tumour progression, metastasis and resistance to apoptosis." (PMID 41261348, 2025). "Chrysotoxine (CTX) has two mechanisms through which it accomplishes an anti‐cervical cancer effect; it is inducing ferroptosis and preventing the PI3K/AKT/mTOR signaling pathway." (PMID 40717210, 2025). "Our results demonstrate that PPP1R13L promotes cervical cancer cell proliferation, epithelial-mesenchymal transition, cycle progression, and glycolysis via the PTEN/AKT/mTOR pathway." (PMID 40014097, 2025). "In HeLa human cervical cancer cells, propofol exerted its antitumor effect by inducing endoplasmic reticulum (ER) stress and regulating the AMPK/mTOR signaling pathway to block autophagosome–lysosome fusion and promote autophagosome accumulation." (PMID 38482052, 2024). "Our cellular experiments showed that naringenin can inhibit the proliferation, migration, and invasion of cervical cancer cells, and further western blot confirmed that naringenin achieves these effects by EGFR/PI3K/AKT/mTOR pathway." (PMID 38253629, 2024). "However, it is unknown whether TRIM21 can regulate the AKT/mTOR pathway in cervical cancer." (PMID 39103348, 2024). "Metformin treatment activated the AMPK/mTOR signaling pathway in two cervical cancer cell lines, whereas the AMPK inhibitor dorsomorphin or the mTOR activator MHY1485 had the opposite effect." (PMID 38831454, 2024). "In cervical cancer, CD38 enhances phosphorylation of PI3K, AKT and mechanistic target of rapamycin (mTOR), all crucial for cell survival and proliferation, mediated by its NADase activity impacting NAD levels and cellular metabolism." (PMID 39364393, 2024). "Abemaciclib suppresses cervical cancer cell growth and promoted apoptosis via the suppression of CDK4/6-Rb-E2F and mTOR pathways." (PMID 38170401, 2024). "MiR-21 was up-regulated and regulated multiple signaling pathways in cervical cancer, including TNF-α/caspase-3/caspase-8, PI3K/AKT/mTOR, and RAS/MEK/ERK pathways." (PMID 39060960, 2024).
cervical carcinoma (continued). "In cervical cancer, FNDC3B can promote the ability of proliferation and metastasis of tumor cells through activating PI3K/mTOR signaling pathway." (PMID 38581008, 2024). "mTOR and S6K1 signalling pathways are considered the most appropriate targets against natural compounds for cervical cancer treatment." (PMID 37836581, 2023). "The combined evidence from these studies suggests genistein acts to inhibit proliferation and survival of cervical cancer cells through inhibition of ERK, Akt and mTOR." (PMID 38201463, 2023). "In cervical cancer cells, LINC00861 inhibits tumor progression and EMT by acting as a ceRNA for miR-513b-5p and modulating the PTEN/AKT/mTOR pathway." (PMID 37303739, 2023). "The pathway analysis revealed the correlation between CD36 and the PI3K/AKT/mTOR signaling pathway, which is consistent with previous research and further strengthens the potential role of CD36 in HPV infection and cervical cancer." (PMID 37795297, 2023). "Functional studies in cervical cancer cell lines identified NBPF1 regulation of cell invasion and apoptosis by activating PI3K/mTOR signaling pathways, which are key mechanisms in cancer progression." (PMID 37454130, 2023). "The PI3K/AKT/mTOR pathway can promote migration and induce EMT in numerous types of tumors, including cervical cancer." (PMID 36911370, 2023). "Baicalein inhibits cervical cancer cell growth through regulating circHIAT1/miR-19a-3p, which targets the PI3K/Akt/mTOR pathway." (PMID 37940982, 2023). "Further, upregulation of ADAMTS12 gene can affect mTOR signaling pathway, suggesting that the ADAMTS12 gene can provide a new target for diagnosis and treatment of cervical cancer." (PMID 37642715, 2023). "The high expression of ERBB3 in cervical cancer tissues (especially HPV-positive and adenocarcinoma-related) promoted the activation of the PI3K/AKT/mTOR pathway." (PMID 36911370, 2023). "In cervical cancer cells, RTKs, including EGFR and PDGFRα, were significantly downregulated and Akt-mTOR activation was largely inhibited after TN treatment." (PMID 39282148, 2022). "In some studies concerning cervical cancer, the theory that curcumin enhances radiosensitivity by inhibiting GLUT1-induced PI3K/AKT/mTOR pathway or MAPK/mTOR/ULK1 pathway and subsequently activating autophagy has also been confirmed." (PMID 35992779, 2022). "Previous studies report a role played by Fib-3 on human cervical cancer cell growth and metastasis in vitro and in vivo via PI3K-Akt-mTOR signal transduction pathway." (PMID 35795376, 2022). "GSEA of the RNA-seq data in the present study revealed that a total of 2458 genes were dysregulated in TN-treated cervical cancer cells, of which the RTKs and PI3K-Akt-mTOR cascades were significantly downregulated." (PMID 39282148, 2022). "In cervical cancer, miRNA-199a targets the 3′-untranslated region of CD276 and regulates its expression, and then activates the AKT/mTOR signaling pathway to inhibit tumor proliferation." (PMID 36358792, 2022). "Bacterial cyclodipeptides (CDPs) exert cytotoxic effects in human cervical cancer HeLa cells, primarily by blocking the PI3K/Akt/mTOR pathway, but downstream responses comprising gene expression remain unstudied." (PMID 35359411, 2022). "Gene set enrichment analysis (GSEA) of RNA sequencing data of differentially expressed genes (DEGs) in TN-treated cervical cancer cells implied that DEGs were enriched in the receptor tyrosine kinase (RTK) signaling and PI3K-Akt-mTOR cascade." (PMID 39282148, 2022). "FGFR pathway is a key upstream pathway of PI3K/AKT/mTOR pathway, and abnormal FGFR pathway are very common in cervical cancers, which give us a new sight for our next mechanism research." (PMID 35458629, 2022). "The PI3K-Akt-mTOR pan inhibitor, LY294002 66, intensified SKI-V-induced cytotoxicity and apoptosis in pCCa-1 primary cervical cancer cells." (PMID 35541904, 2022).
cervical carcinoma (continued). "RCE-4, the main active composition of Reineckia carnea, exerted an anti-cervical cancer effect on HeLa cells by reducing PI3K, Akt, mTOR, and NF-κB p65 phosphorylation levels." (PMID 35214097, 2022). "As shown, Akt, S6, and 4EBP1 phosphorylation as well as mTOR and PI3K expression were significantly downregulated in shESM1-expressing cervical cancer cells." (PMID 36522312, 2022). "Previously, knockdown of HK2 in cervical cancer cells has been observed to inhibit expression of AKT and mTOR, which are involved in cancer progression." (PMID 35184747, 2022). "Despite these limitations, our study validated the presence of immune dysregulation in TB of cervical cancer, especially the dysregulation of the PI3K/Akt/mTOR signaling pathway." (PMID 36354662, 2022). "Co-immunoprecipitation (Co-IP) assay and rescue assay confirmed that CD155 can interact with AKT to form CD155/AKT complex, and further promote the proliferation of cervical cancer cells and inhibit autophagy through AKT/mTOR and NF-κB pathways." (PMID 34164340, 2021). "The mTOR signaling-related gene, STK11, previously reported by our group as a poor prognostic factor for cervical cancer, was altered significantly more frequently in patients with NECC than in those with SCC (16.0% vs. 4.4%, p < 0.05)." (PMID 33802174, 2021). "Consistently, during SPAG5 taxol treatment for cervical cancer, SPAG5 was observed to regulate mTOR activity." (PMID 34162370, 2021). "At the same time, luteoloside inhibited mTOR and activated p38 mitogen-activated protein kinase (MAPK) signaling pathways to exert anti-cervical-cancer effects." (PMID 34680171, 2021). "Some of these compounds decreased p-PI3K while increasing PTEN expression, such as Kaempferol in hepatocarcinoma and cervical cancer cells and EGCG in pancreatic cancer cells, reinforcing the inhibition of mTOR signaling by these two axis." (PMID 33918290, 2021). "In order to verify the role of TGFβ in baicalein suppressing cervical cancer, SB431542, a TGFβ inhibitor, was employed to further assess the effect of baicalein on the expression of p-mTOR, mTOR, and E-cadherin." (PMID 33777154, 2021). "Genistein enhanced the activity of cisplatin by inhibiting the expression of the AKT/mTOR pathway, p-p70S6K1 and p-4E-BP1, which led to the growth inhibition of cervical cancer cells." (PMID 34680171, 2021). "In a study of cervical cancer, it was demonstrated that TRIM28 promoted the growth of cervical cancer cells by activating the mTOR signaling pathway." (PMID 33817325, 2021). "In this study, silencing CD155 in cervical cancer cells significantly reduced p-AKT, p-mTOR, p-P7S60, and p-4EBP1 expression levels and cell proliferation whereas autophagy and apoptosis were significantly increased compared with control cells." (PMID 34164340, 2021). "In human cervical cancer, the activation of the PI3K/AKT/mTOR pathway, the main system utilized by cancer cells, was reduced following fucosterol treatment." (PMID 32429354, 2020). "The role of growth factors, especially VEGF, with the mTOR pathway through CAF stimulation has yet to be studied in ovarian and cervical cancers." (PMID 31947591, 2020). "Studying the role of TGF-b, Chen and colleagues found that inhibiting the mTOR signaling leads to downregulation of pyruvate kinase M2 (PKM2), which is needed to induce EMT in cervical cancer cells." (PMID 31947591, 2020). "To elucidate how E6 and its binding protein, IRF-1, affect the PI3K/AKT pathway in cervical cancer cells, we investigated the role of PDK1, Akt, mTOR, and 4E-BP1, which are downstream signalling regulators of PI3K." (PMID 33076322, 2020).
cervical carcinoma (continued). "Autophagy mediates enhanced AMPK activity in human breast and cervical cancer cells and activated AMPK initiate autophagosome formation by activating PIK3C3/VPS34 complex or by inhibiting mTOR and regulate ERK1/2." (PMID 32184774, 2020). "Present study planned to investigate the function of GHET1 in cervical cancer and its mechanism in regulating AKT/mTOR and Wnt/β-catenin signaling pathways." (PMID 31682716, 2020). "In cervical cancer, gastric carcinoma proliferation enhancing transcript 1 (GHET1) regulates AKT/mTOR and Wnt/β-catenin signaling pathways by stabilizing the interaction of E2F6 and IGF2BP2." (PMID 32391379, 2020). "In summary, we elucidate the therapeutic potential of a newly found mTOR/S6K1 inhibitor, RAME, for the treatment of cervical cancer patients." (PMID 31387554, 2019). "Several recent studies have shown that treatment with rapamycin, the most established mTOR/S6K1 inhibitor, induces autophagy and apoptotic cell death in cervical cancer cells as well as synergistic therapeutic responses in combination with cisplatin." (PMID 31387554, 2019). "Previous studies have shown that melittin downregulates PI3K/AKT/mTOR and MAPK signaling pathways, thereby leading to apoptosis in several tumor cells such as liver and cervical cancers and inhibits the metastatic ability of cancer cells." (PMID 30866426, 2019). "The mTOR/S6K1 signaling pathway is often activated in cervical cancer, and thus considered a molecular target for cervical cancer therapies." (PMID 31387554, 2019). "Similar to cervical cancer, the PI3K/AKT/mTOR pathway belongs to the most frequently altered signaling pathways in HNSCC." (PMID 31058807, 2019). "Immunostaining analyses have shown that p-mTOR, p-p70S6K1, and p-S6 are highly detected in HPV-positive lesions and cervical cancer cell lines, and these contribute to the survival of cervical cancer cells." (PMID 31387554, 2019). "Some studies also indicated that SC66 effectively inhibited the phosphorylation levels of AKT through disruption of mTOR signaling, and therefore contributes to decrease the expressions of p-GSK-3β and p-FOXO1 in human cervical cancer." (PMID 31168297, 2019). "In cervical cancer, the PI3K/Akt/mTOR pathway is often dysregulated and is considered a promising target for therapy." (PMID 29874795, 2018). "PI3K/AKT/mTOR and MAPK/ERK signaling pathways are reported to involved in malignant progress of cervical carcinoma." (PMID 28490807, 2017). "There is a strong rationale to therapeutically target the PI3K/Akt/mTOR and MAPK/ERK pathways in cervical carcinoma since they are highly deregulated in this disease." (PMID 28490807, 2017). "Collectively, these data clearly demonstrated the antitumor activity of Zey in cervical carcinoma cells, which is most likely via the regulation of PI3K/Akt/mTOR and MAPK/ERK pathways." (PMID 28490807, 2017). "The three members of miR-99 family show relevance in cervical carcinoma since it has been shown a down-regulation of mRNA and protein of Homeobox A1 (HOXA1) and mTOR via 3′UTR in HaCaT cells." (PMID 28216603, 2017). "Previous study by our group have demonstrated that Zeylenone (Zey) exhibited strong suppressive activity on PI3K/AKT/mTOR and MAPK/ERK signaling, providing a foundation to investigate its antitumor activity in cervical carcinoma." (PMID 28490807, 2017). "miR-7, miR-9, miR-15, miR-34, miR-99, and miR-125 families participate in MAPK, PI3K-AKT, Jak/STAT3, and mTOR cell-signaling pathways’ regulation as well as in apoptosis, cell cycle, autophagy, and EMT potentiating cervical carcinoma development." (PMID 28216603, 2017). "To confirm these results, we further analyzed the tumor expression of mTOR, HIF-1α, c-Myc, and PKM2 in matched pairs of primary cervical cancer biopsies by western blotting analysis." (PMID 27492148, 2016).
cervical carcinoma (continued). "In this study, we examined the correlation between mTOR, HIF-1α, c-Myc, and PKM2 expression and the response to cisplatin-based NACT in patients with stage IB2 or IIA2 cervical cancer." (PMID 27492148, 2016). "The main objective of this study was to obtain evidence of PGRN regulation of the mTOR signaling pathway and its contribution to PGRN-mediated transformation and progression of cervical cancer." (PMID 27517315, 2016). "In this study, we demonstrated that mTOR, HIF-1α, c-Myc and PKM2 expression were significantly downregulated in post-chemotherapy cervical cancer tissues compared with matched pairs of pre-chemotherapy biopsies." (PMID 27492148, 2016). "Our data indicate a positive relation of PGRN level with level of phosphorylated mTOR in both CSC and CAC, which strongly suggests a potential relationship between PGRN and mTOR signaling in the progression of cervical cancer." (PMID 27517315, 2016). "We found level of PGRN correlated with that of phosphorylated mTOR in cervical cancer, and PGRN stimulated the phosphorylation of mTOR and activation of PI3K/Akt/mTOR signaling in cervical cells." (PMID 27517315, 2016). "In the present study, we first evaluated the effect of chemotherapy on the expression of mTOR, HIF-1α, c-Myc, and PKM2 in cervical cancer samples." (PMID 27492148, 2016). "PGRN promoted the phosphorylation of mTOR and activated mTOR signaling in human cervical mucosa epithelial cells and cervical cancer cells, and TNFR2 was needed for PGRN-stimulated mTOR signaling." (PMID 27517315, 2016). "Using paired tumor samples (pre- and post-chemotherapy) from 36 cervical cancer patients, we examined mTOR, HIF-1α, c-Myc, and PKM2 expression in cervical cancer samples and investigated the response to cisplatin-based NACT." (PMID 27492148, 2016). "As a prospective inhibitor of AKT/mTOR, OP-B can also exhibit autophagy-dependent antitumor effects via repression AKT/mTOR signaling pathway in human cervical cancer HeLa cells." (PMID 28119606, 2016). "Preclinical studies have shown that both the mTOR inhibitor (rapamycin) and EGFR-tyrosine kinase inhibitor (erlotinib) can induce growth delay of xenografted HPV-containing cervical carcinoma cells." (PMID 26022660, 2015). "In cervical cancer the expression of miR-99b and miR-125a are opposite, suggesting a specific selection of miR-125a over miR-99b, resulting in HOXA1 and mTOR overexpression." (PMID 26057746, 2015). "Individual treatment of ECGC significantly reduced the level of phosphorylated mTOR, p70S6K1, 4E-BP1, and Akt in cervical cancer cells, while individual cisplatin treatment significantly increased their levels compared to control." (PMID 25988128, 2014). "A panel of human cervical cancer cell lines was tested for the expression pattern and activation status of PI3K/AKT/mTOR pathway molecules." (PMID 24705275, 2014). "For example, treatment of SiHa (cervical cancer), A549 (lung) and MCF7 (breast) cancer cells with docosahexaenoic acid resulted in autophagy via an induction of AMPK and mTOR inhibition." (PMID 25296977, 2014). "Propofol inhibits activation of the mammalian target of rapamycin (mTOR)/p70S6K pathway and modulates the HOTAIR/miR-129-5p/ribosomal protein L14 (RPL14) axis by decreasing HOTAIR expression, which subsequently inhibits the growth of cervical cancer cells." (PMID 40129947, 2025). "Similarly, in cervical cancer, RBM15 inhibition reduces m6A methylation of OTUB2, leading to the inactivation of the AKT/mTOR pathway, which in turn decreases cell proliferation and metastasis capacity." (PMID 39716068, 2024). "Therefore, we provide evidence for the role of the TRIM21-NCAPH axis in cervical cancer autophagy and proliferation and the involvement of the AKT/mTOR signaling pathway in this process." (PMID 39103348, 2024).